CAV1 (caveolin 1)
Diseases named in the same sentence as CAV1 in open-access papers (continued):
Sharing a sentence is not in itself a finding about the gene and the disease.
psoriasis (continued). "Therefore, we hypothesized that CAV-1 reduction in monocytes may also influence the pathogenesis of psoriasis by modulating cytokine production." (PMID 30644419, 2019). "Our previous study revealed CAV-1 reduction in the epidermis of patients with psoriasis, which leads to enhanced Janus kinase/signal transducer and activator of transcription activation and cytokine production, suggesting that aberrant CAV-1 expression may contribute to psoriatic inflammation." (PMID 30644419, 2019). "Here we re-consider the pathogenesis of psoriasis with a special emphasis on defective Cav-1 expression/distribution in psoriatic skin and analyze whether physical factors which are known to modulate these processes can be applied for treatment of this skin disease." (PMID 30729030, 2019). "Silencing of Cav-1 in keratinocytes in vitro caused an increased expression of different cytokines/chemokines, such as IL-6, CXCL8, and CXCL9, whereas the application of a Cav-1 scaffolding domain peptide in a murine skin model of psoriasis effectively reduces their expression." (PMID 31877626, 2019). "Since such psoriasis-related pro-inflammatory cytokines were high in the serum of patients with psoriasis, it may be reasonable that a cytokine-rich environment in psoriasis would favour CAV-1 reduction in leukocytes/monocytes." (PMID 30644419, 2019). "We found that psoriasis-related cytokines, namely IL-17, IL-22, IL-1β, and TNF-α, reduced CAV-1 expression in human keratinocytes." (PMID 36532050, 2022). "Very low levels of CAV1 have been observed in types of psoriasis such as plaque, pustular, palmoplantar, and nail psoriasis but not in guttate or inverse psoriasis." (PMID 41516288, 2025). "The negative correlation between Cav-1 and collagen expression is also evident in psoriasis where the low levels of Cav-16,9 negatively correlate with high levels of collagen expression in involved and even in uninvolved areas of the skin." (PMID 30729030, 2019). "Since CAV-1 reduction was most prominent in circulating monocytes, we confirmed that CAV-1 mRNA and protein levels in monocytes were purified from PBMCs of patients with psoriasis in comparison with those of healthy subjects by qPCR and immunoblotting." (PMID 30644419, 2019).
cervical cancer (8 papers, 2005 to 2023). A primary or metastatic malignant neoplasm involving the cervix. "In cervical cancer, expression of CAV1 increases, and the long-term survival rate of patients is reduced." (PMID 37907864, 2023). "siROR1 treatment also significantly reduced CAV1 in A431 (vulval epidermoid carcinoma) and HeLa (cervical cancer) cell lines, indicating the involvement of ROR1 in other types of cancer cells." (PMID 26725982, 2016). "Caveolin-1 is commonly downreglulated in cervical cancer cells and its introduction via gene transfer restores caveolin-1 protein expression and impairs growth in SiHa cells, which supports its role as a tumor suppressor gene." (PMID 16248899, 2005). "Cav-1 loses its suppressing role in the development of cervical cancer, including 54 SCCs and 18 adenocarcinomas, by methylation of Cav-1 promoter or other unknown mechanisms." (PMID 31759347, 2019). "Our study demonstrates the key role of LY6K in both clathrin‐ and CAV‐1‐mediated endocytic pathways regulated by TGF‐β and EGF, and it suggests a correlation between LY6K overexpression in cervical cancer cells and poor overall survival." (PMID 37076981, 2023).
COVID-19 (8 papers, 2020 to 2026). A disease caused by infection with severe acute respiratory syndrome coronavirus 2. "The expression pattern of ACE2 and TMPRSS2 genes in the CAV1-positive cluster was consistent with the finding that liver cholangiocytes were associated with liver injury in COVID-19 patients." (PMID 33104520, 2020). "We also observed significantly decreased immunoexpression of Cav-1 (p < 0.0001) in the COVID-19 compared to the CONTROL group." (PMID 35008594, 2021). "This increased expression of Cav-1 was also discovered in our analysis of postmortem COVID-19 patients, further strengthening the role caveolin-mediated transcytosis could be playing in SARS-CoV-2 infection." (PMID 38793666, 2024). "Another relevant finding is the decreased immunoexpression of Cav-1 in the COVID-19 group." (PMID 35008594, 2021). "No statistical difference was observed in the tissue expression of AKT-1, Cav-1, MMP-9, Sphingosine-1, and TGF-β1 when testing COVID-19 and H1N1 groups." (PMID 35008594, 2021). "In addition, CAV1, CDC20, and KIF20A were also identified as hub genes in COVID-19 by other researchers." (PMID 35957855, 2022).
injury (8 papers, 2012 to 2026). Damage inflicted on the body as the direct or indirect result of an external force, with or without disruption of structural continuity. "Therefore, we evaluated whether the protective role of Cav-1-deficient BMMs in acute liver injury was related to enhanced BMMs recruitment." (PMID 40430042, 2025). "In this study, we demonstrated elevated BMMs recruitment coupled with upregulated Cav-1 expression in CCl4-induced acute liver injury." (PMID 40430042, 2025). "Following clodronate liposome-mediated hepatic macrophage depletion, the adoptive transfer of Cav-1 KO BMMs demonstrated therapeutic efficacy in CCl4-induced acute liver injury." (PMID 40430042, 2025). "Down‐regulation of Cav‐1 can enhance the phosphorylation levels of p38 and the expression of NF‐κB and exacerbate LPS‐induced acute lung injury." (PMID 34114328, 2021). "It was also reported that CAV1 and CAV2 levels are elevated in endothelial cells in a mouse model of traumatic brain injury." (PMID 26492081, 2015).
lung squamous cell carcinoma (8 papers, 2012 to 2023). "50.7% of squamous cell lung cancer (SCC) tumors showed strong expression of CAV1 in the tumor-associated stromal cells, whereas only 15.1% of adenocarcinomas (AC) showed a strong CAV1 expression (p < 0.01)." (PMID 29850392, 2018). "CAT, ENO1, NQO1, P4HB, and PDIA6 were unique to LUAD, while CAV1, GAPDH, GPX2, GPX3, and PDIA4 exhibited consistent trends in differential expression in both LUAD and lung squamous cell cancer, significant prognostic survival prediction (p<0.05), and excellent classification effectiveness." (PMID 37955007, 2023).
neuroblastoma (8 papers, 2007 to 2022). Neuroblastoma (NB) is the most common solid, extracranial childhood tumor. "More recently, we have demonstrated that JEV is internalized in neuron-derived rat neuroblastoma B104 cells and human neuroblastoma SK-N-SH cells through a caveolin-1-dependent pathway." (PMID 32538298, 2020). "The NO donor diethylenetriamine (DETA)/NO upregulated cav-1 in hypoxic human SK-N-MC neuroblastoma cells." (PMID 30572925, 2018). "In hypoxic human SK-N-MC neuroblastoma cells, iNOS-induced NO production reduces the expression of cav-1." (PMID 30572925, 2018). "In this context, it is especially relevant that Estrogen Receptor α or ERα (CpG 58), a nuclear protein implicated in glucose homeostasis, has been reported to silence Cav-1 gene through CpG hypermethylation of its promoter in human neuroblastoma cells." (PMID 24751908, 2014). "Indeed, CAV1 overexpression reduces NO production in neuroblastoma SK-N-MC cells in hypoxia (2% O2)." (PMID 32825247, 2020). "N-type CaV2.2 channels are co-expressed with CaV1 and CaV3 channels in neuroblastoma cells." (PMID 27342111, 2016). "We demonstrate that in neuroblastoma cells, MoPrP105-132 co-localises with cholera toxin subunit B (CTxB), which binds to the ganglioside GM1 and caveolin-1, markers of specialised microdomains called lipid rafts." (PMID 18034899, 2007). "When lipid rafts were isolated from neuroblastoma cells that had been pre-treated with squalestatin, most of the MoPrP105-132 was detected in the non-raft fraction, while CTxB and caveolin-1 were present in both raft and non-raft fractions." (PMID 18034899, 2007). "Squalestatin-treatment of neuroblastoma cells greatly reduced the amounts of MoPrP105-132 that co-localised with either CTxB or with caveolin-1 indicating the most of the peptide was no longer present in lipid rafts." (PMID 18034899, 2007). "Indeed, no significant amounts of caveolin-1 were detected in human neuroblastoma cells by Western blotting (not shown)." (PMID 28903310, 2017).
pneumonia (8 papers, 2012 to 2024). An acute, acute and chronic, or chronic inflammation focally or diffusely affecting the lung parenchyma, caused by an infection in one or both of the lungs (by bacteria, viruses, fungi, or mycoplasma.). "Among the 27 focal adhesion-related dysregulated proteins (18 up-regulated and 9 down-regulated), thrombospondin-1 (THBS1) and caveolin-1 (CAV1) have been reported to be associated with pneumonia." (PMID 36387401, 2022). "Biomarkers including NEK7 and CAV1 were associated with the risk of pneumonia." (PMID 38137330, 2023). "Caveolin 2, which localizes to the Golgi complex but redistributes to plasma membrane, caveolae and rafts when co-expressed with caveolin 1, is a potential key molecule related to the Pseudomonas infection causing pneumonia in patients with cystic fibrosis and other immunocompromising conditions." (PMID 22330747, 2012). "Our study reveals novel roles for PKCα and eNOS uncoupling and strategies to prevent the loss of eNOS fidelity such as increasing caveolin-1 or the production of reactive oxygen species may be of significant benefit in reducing the morbidity and mortality of G+-induced pneumonia and pulmonary edema." (PMID 25020117, 2014). "In addition, Cav–1 promoted bacterial elimination during acute pneumonia and chronic colonization." (PMID 35911737, 2022). "Absence of Cav–1 reduced PMN recruitment and increased production of inflammatory cytokines during the acute phase of pneumonia, affecting host resistance to infection." (PMID 35911737, 2022).
renal carcinoma (8 papers, 2003 to 2025). A carcinoma arising from the epithelium of the renal parenchyma or the renal pelvis. "In renal cancer, Cav1 has been shown to be a tumor progression factor, but in general its involvement in kidney tumorigenesis has been investigated relatively little." (PMID 29084770, 2017). "Apparent from the results of our current study was the cytoplasmic localisation of the overexpressed caveolin-1 within the renal carcinoma cells." (PMID 14612902, 2003). "Regarding other candidate genes, such as HAMP and CAV1, although numerous studies have demonstrated their potential roles in RCC and their adverse effects on the prognosis of ccRCC patients, their impact on the malignant phenotype of renal cancer cells in our in vitro model was not significant." (PMID 40341358, 2025).
small cell lung carcinoma (8 papers, 2013 to 2025). Small cell lung cancer (SCLC) is a highly aggressive malignant neoplasm, accounting for 10-15% of lung cancer cases, characterized byrapid growth, and early metastasis. "In another study, CAV1 was found to be reduced in small cell lung cancer cell lines, but in 76% of NSCLC cell lines, it is still expressed." (PMID 29190968, 2017).
brain tumors (7 papers, 2010 to 2025). "The data reported in this study on the co-localization of P-gp with caveolin-1 provide the morphological evidence of the association between P-gp and caveolin-1 in brain tumor endothelia and highlight the dynamic nature of this interaction." (PMID 20815915, 2010). "Several studies have reported that CAV1 can alter the molecular basis of the pathobiology of brain tumors, especially the malignant glial subtypes." (PMID 40143204, 2025). "In the realm of neuro-oncology, emerging evidence underscores the significance of caveolae and caveolins, particularly Cav-1 in the pathogenesis of brain tumors." (PMID 40243482, 2025). "In addition, double immunolabeling was carried out with antibodies to P-gp and caveolin-1 by immunofluorescence laser scanning confocal microscopy to ascertain whether there is any association between these molecules in the microvessels of brain tumors." (PMID 20815915, 2010). "The studies use immunolabeling of brain tissues with antibodies against P-gp and caveolin-1, and evidence was found for the expression of P-gp on the luminal membrane of the capillary endothelium in brain tumors." (PMID 20815915, 2010). "Importantly, membranous CAV1 expression has been recognized as a marker for brain tumors with high-grade malignancies." (PMID 37047005, 2023). "We use fucoidan-based nanocarriers targeting endothelial P-selectin to induce caveolin-1-dependent transcytosis and thus nanocarrier transport into the brain tumour microenvironment in a selective and active manner, the efficiency of which is increased by radiation treatment." (PMID 36864161, 2023). "However, in brain tumors, there are few reports about the interaction between P-gp and caveolin-1." (PMID 20815915, 2010). "The aim was to assess the serum hypoxia biomarkers HIF-1α, VEGF, osteopontin, erythropoietin, caveolin-1, GLUT-1, and LDH pre- and post-radiotherapy in patients with brain tumors." (PMID 36121548, 2022). "The main target of this study was to assess the circulating serum hypoxia biomarkers HIF-1α, VEGF, osteopontin, erythropoietin, caveolin-1, GLUT-1, and LDH pre- and post-radiotherapy in patients with brain tumors." (PMID 36121548, 2022).
invasive ductal carcinoma (7 papers, 2007 to 2020). "Cav-1 expression was markedly reduced in invasive ductal carcinoma and observed to progressively correlate in a grade- and stage-dependent manner (respectively)." (PMID 26543228, 2016). "As a proof, ectopic expression of CAV1 in invasive ductal carcinoma cells (MCF7) suppressed NRF2 expression, the induction of MnSOD, and decreased aerobic glycolytic phenotype as measured by extracellular acidification and lactate output." (PMID 27852311, 2016). "In invasive ductal carcinoma, CAV1 is reduced at the early stage of progression and predicts poor survival outcome." (PMID 27852311, 2016). "We found that Cav-1 protein levels in invasive ductal carcinoma are reduced early during tumor progression." (PMID 26543228, 2016). "Twenty-two cases (68.75%) of invasive ductal carcinoma showed high levels (score≥1.5) of caveolin-1 staining, whereas low expression of caveolin-1 (score <1.5) was noted in 10 cases (31.25%)." (PMID 26172389, 2015). "They reported significantly higher expression of Caveolin-1 in both intraductal carcinomas (p > 0.001) and infiltrating ductal carcinomas (93.3%, p < 0.001) as well as in lymph node metastases (p < 0.001) relative to normal breast epithelium." (PMID 17915016, 2007).
keloid (7 papers, 2014 to 2025). An irregularly shaped, elevated mark on the skin caused by deposits of excessive amounts of collagen during wound healing. "In keloid fibroblasts, reduced CAV-1 leads to upregulation of the transcription factor RUNX2, which is a potential regulator of increased ECM production in keloids and is associated with fibrosis." (PMID 35614943, 2022). "Low expression of CAV-1 decreases cell stiffness, but increases the contractility and migration ability of keloid fibroblasts." (PMID 35614943, 2022). "CAV-1 expression was markedly decreased in HTS and keloid-derived human fibroblasts, and reduced CAV-1 expression mediates fibrotic responses by modulating TGF-β signaling, similar to SSc." (PMID 36532050, 2022). "Treatment of keloid with trichostatin A led to an increase in CAV1, elevated cell stiffness, and a decrease in their migratory ability." (PMID 31216669, 2019). "Although other reports have found that mTOR is activated in Cav-1 knock out CAFs and keloids, the newly identified axis in CAFs (Cav-1 to mTOR to RB) requires further clarification." (PMID 25202343, 2014). "This consistently leads to a reduction of the CAV1 content in affected skin areas, causing the established hallmark of hypertrophic scarring (HTS) and keloids (KE), as well as overexpression of RUNX2, which promotes the formation of the cartilage-like hyalinated scar tissue." (PMID 41246307, 2025). "In addition, the low expression of caveolin-1, a cell membrane protein, was involved in cell softening and aberrant responsiveness to mechanical stress in keloid fibroblasts." (PMID 34067386, 2021). "In keloid FBs, decreased CAV1 increases the expression of the transcription factor RUNX2 responsible for osteogenesis, which is a potential regulator of increased ECM production in keloids and is associated with fibrogenesis." (PMID 31216669, 2019). "Phosphorylated CAV-1 and ROCK are upregulated in the peripheral skin tissue surrounding keloids, but not in normal skin and keloid sites, and CAV-1/ROCK expression correlates with a high inflammatory and proliferative status." (PMID 36532050, 2022).
metastatic prostate carcinoma (7 papers, 2013 to 2023). A carcinoma that arises from the prostate gland and has spread to other anatomic sites. "The reverse effect was observed in stromal cells in advanced metastatic prostate cancer, where the expression of CAV-1 was decreased." (PMID 37298472, 2023). "Caveolin-1 (Cav-1) is overexpressed in aggressive and metastatic prostate cancer (PCa) and induces PCa cell proliferation." (PMID 27331874, 2016). "Cav1 expression is elevated in metastatic prostate cancer (PCa) cells and Cav1 has been evaluated as a prognostic marker of aggressive PCa." (PMID 25942420, 2015). "Immunohistochemical analysis of human tissue specimen further revealed that although Cav1 expression is mostly reduced in the tumor stroma of advanced and metastatic prostate cancer, the vascular compartment still expresses high levels of Cav1." (PMID 25985209, 2015). "In yet another study performed on plasma samples from metastatic prostate cancer patients, caveolin-1 (CAV1) was found on 5–10% of large EV (1–10 μm) isolated by filtration, but with a size profile similar to the 10,000 g pellet, whereas it was barely detectable in healthy controls." (PMID 32731639, 2020). "Caveolin-1 overexpression exists in primary and metastatic prostate cancer." (PMID 30424755, 2018).